FAR2 (fatty acyl-CoA reductase 2)
Description:
Catalyzes the reduction of saturated but not unsaturated C16 or C18 fatty acyl-CoA to fatty alcohols (FAls). A lower activity can be observed with shorter fatty acyl-CoA substrates. Can produce very long-chain and ultra long-chain FAls, regardless of whether they have a straight or branched chain. Involved in the production of ether lipids/plasmalogens and wax monoesters whose synthesis requires FAls as substrates.
Synonyms: MLSTD1; FLJ10462; SDR10E2; HEL-S-81
Tractability: Antibody: UniProt predicts a signal peptide or a membrane-spanning region. PROTAC: ubiquitination databases record sites on it; its protein half-life has been measured.
Gene: Protein-coding gene on chromosome 12 (29,149,016 to 29,341,121, forward strand). Ensembl gene ENSG00000064763.
Subcellular location: Peroxisome membrane
Subcellular location (Human Protein Atlas): Golgi apparatus; Nucleoli
Pathways (Reactome):
Metabolism: Wax biosynthesis
Gene Ontology:
Molecular function: alcohol-forming very long-chain fatty acyl-CoA reductase activity; oxidoreductase activity; alcohol-forming long-chain fatty acyl-CoA reductase activity
Biological process: long-chain fatty-acyl-CoA metabolic process; wax biosynthetic process
Cellular component: peroxisomal membrane; peroxisome
Genetic constraint (gnomAD): Loss-of-function variants: 15 observed, 44.73 expected, observed/expected ratio (o/e) 0.34, 90% interval 0.22 to 0.52. The upper end of that interval is the gene's LOEUF score, 0.52, which puts it in group 2 of 6, group 1 being the genes least tolerant of losing a copy. Missense variants: 444 observed, 573.96 expected, observed/expected ratio (o/e) 0.77, 90% interval 0.71 to 0.84. Synonymous variants: 190 observed, 196.25 expected, observed/expected ratio (o/e) 0.97, 90% interval 0.86 to 1.09.
Homologues: Orthologues: chimpanzee FAR2 (99% identical), macaque FAR2 (96% identical), dog FAR2 (93% identical), pig FAR2 (92% identical), rabbit FAR2 (90% identical), mouse Far2 (88% identical), rat Far2 (88% identical), guinea pig FAR2 (85% identical), Drosophila melanogaster CG5065 (38% identical), Caenorhabditis elegans fard-1 (35% identical), Drosophila melanogaster CG12268 (35% identical), Drosophila melanogaster CG14893 (34% identical), and 14 more. Paralogues in human: FAR1 (59% identical).
Diseases named in the same sentence as FAR2 in open-access papers:
FAR2 is named in the same sentence as 26 diseases in open-access papers, as found by Europe PMC text mining. Sharing a sentence is not in itself a finding about the gene and the disease. The quoted sentences say what the papers report.
Insulin resistance (6 papers, 2019 to 2025). Increased resistance towards insulin, that is, diminished effectiveness of insulin in reducing blood glucose levels. "A differentially methylated CpG site on the fatty acyl CoA reductase 2 (FAR2) gene of chromosome 12 has been reported to be associated with antipsychotic-induced insulin resistance in subjects with bipolar disorder." (PMID 38046756, 2023). "Fatty acyl CoA reductase 2 (FAR2) gene methylation changes in peripheral blood cells were reported to be associated with atypical antipsychotic-induced insulin resistance and lipid metabolism." (PMID 31849831, 2019). "The only studies that used this approach so far allowed to discover a differentially methylated site in the fatty acyl CoA reductase 2 (FAR2) gene that was associated with insulin resistance and another site in the cadherin-like 22 (CDH22) gene that was associated with MetS." (PMID 38419113, 2024). "In another study analyzing DNA methylation changes in candidate genes, Burghardt and colleagues used epigenome-wide association studies to identify a hypomethylated CpG site in fatty acyl Coa reductase 2 (FAR2) associated with insulin resistance as measured by homeostatic model assessment." (PMID 31671770, 2019). "Fatty Acyl-CoA Reductase 2 (FAR2) is a key gene associated with β-oxidation of fatty acids and translocation of acetyl-CoA, and it has been associated with insulin resistance in humans." (PMID 39847436, 2025).
alopecia (2 papers, 2017 to 2018). Hair loss usually from the scalp. "Mice that have a severe hypomorphic allelic mutation for fatty acyl CoA reductase 2 develop a relatively mild form of patchy alopecia on the dorsal trunk and diffuse hair thinning on the ventral body surface." (PMID 30372477, 2018). "Mice with null mutations in their fatty acyl CoA reductase 2 (Far2tm2b(KOMP)Wtsi/2J) gene were found to consistently develop focal alopecia as adults on the dorsal skin extending distally from the base of the ears." (PMID 28700664, 2017). "In a large scale screen for skin, hair, and nail abnormalities in null mice generated by The Jackson Laboratory’s KOMP center, homozygous mutant Far2tm2b(KOMP)Wtsi/2J (hereafter referrred to as Far2-/-) mice were found to develop focal areas of alopecia as they aged." (PMID 30372477, 2018). "In a survey looking for skin abnormalities in genetically engineered mice, the Knockout Mouse Project (KOMP), mice with patchy alopecia were identified that lacked function of the fatty acyl coA reductase 2 (Far2) gene." (PMID 30372477, 2018).
agammaglobulinemia (1 paper, 2024). A decreased level of serum immunoglobulins. "As Sanger sequencing confirmed the segregation of the FAR2 variant with symptoms in patient 2 and as loss of FAR2 function is not linked to neurological disorder or agammaglobulinemia, we excluded it from being causal for these patients." (PMID 37943617, 2024).
atopic dermatitis (1 paper, 2018). "Some of lipid metabolic genes discovered in our analysis were also reported as declined genes in patients with psoriatic (ACSBG1, ALOX15B, ELOVL3, FADS1, FADS2, and THRSP) or atopic dermatitis (CYP4F8, ELOVL3, FADS1, FADS2, FAR2, and HAO2)." (PMID 30021930, 2018).
cervical cancer (1 paper, 2022). A primary or metastatic malignant neoplasm involving the cervix. "Among the five genes, the expression of ALOX12B and F5 was decreased, while that of CA9, FAR2 and TDO2 was relatively elevated in cervical cancer samples, as indicated by the IHC results." (PMID 35626004, 2022). "In current study, we identified a reliable metabolism-related signature composed of ALOX12B, CA9, FAR2, F5 and TDO2 for the prognosis and anti-tumor immunity in cervical cancer." (PMID 35626004, 2022).
diabetic nephropathy (1 paper, 2018). "However, in human patients, increased expression of FAR2 is associated with IgA nephropathy, lupus nephritis, and diabetic nephropathy." (PMID 30372477, 2018).
intestinal cancer (1 paper, 2020). "This could be particularly important in the context of intestinal cancer were FAR2 mRNA levels have been shown to be high compared to other tissues." (PMID 32443825, 2020).
lymphoma (1 paper, 2020). A malignant (clonal) proliferation of B- lymphocytes or T- lymphocytes which involves the lymph nodes, bone marrow and/or extranodal sites. "In addition to AGPS, elevated expression of FAR1, FAR2, and GNPAT, all of which are involved in ether phospholipid biosynthesis, was observed in aggressive lymphoma cells derived from lymphoma patients who were refractory to oxidative stress-inducing therapy." (PMID 32674458, 2020).
cancer (4 papers, 2019 to 2022). A tumor composed of atypical neoplastic, often pleomorphic cells that invade other tissues. "Interestingly, FAR1 and FAR2 were overexpressed in all cancer cells compared to primary cells, at rather similar levels for each cancer cell type (8- to 10-fold in Colo 201; 12-fold in HT29; 5-fold in LS174 and 8- and 12-fold in SW480)." (PMID 32443825, 2020). "According to our results, the increase in PE plasmalogens could be explained by overexpression of the key plasmalogen synthesis enzymes, FAR1, FAR2, and AGPS, in all cancer cell lines." (PMID 32443825, 2020). "Western blot analysis showed that FAR1, FAR2, and AGPS protein expression was consistently enhanced in all cancer cell lines compared to primary cells, although these differences were statistically different in all tumor cell lines simultaneously only for FAR1." (PMID 32443825, 2020).
infection (4 papers, 2014 to 2025). The state of being infected such as from the introduction of a foreign agent such as serum, vaccine, antigenic substance or organism. "To understand the role of Hp-FAR-2 in infection, we investigated the genome of H. polygrus and found it to encode for six FARs, including Hp-FAR-2 and Hp-FAR-1." (PMID 40501701, 2025). "Recombinant FAR-1 and FAR-2 were co-injected into adult flies, mimicking an EPN infection with delivery of the protein and pathogenic bacteria into the hemocoel." (PMID 34714893, 2021). "We hypothesize that Hp-FAR-2 may be released during infection to sequester omega-3 and omega-6 fatty acids, aiding in parasite growth and survival and modulating inflammatory reactions in the host." (PMID 40501701, 2025). "In addition to a one-time injection of recombinant of FAR-1 and FAR-2, we also determined the outcome of infection using transgenic flies expressing either FAR-1 or FAR-2." (PMID 34714893, 2021). "We conclude that FAR1 and FAR2 are not necessary for infection-associated lipid body mobilisation in M. oryzae, which is instead dependent on autophagy." (PMID 24949933, 2014).
bacterial infection (2 papers, 2021 to 2025). "To determine immune modulation by Hp-FAR-2, we investigated if Hp-FAR-2 would influence D. melanogaster survival against bacterial infection of Gram-positive extracellular pathogen Streptococcus pnueumoniae (S.p.)." (PMID 40501701, 2025). "To establish the mechanism by which FAR-1 and FAR-2 elicit their immunomodulatory effects, we evaluated several readouts of immunity including phenoloxidase (PO) activity and melanization, which are essential immune defenses during a bacterial infection." (PMID 34714893, 2021).
neurodevelopmental disorder (2 papers, 2023). A behavioral and cognitive disorder with onset during the developmental period that involves impaired or aberrant development of intellectual, motor, or social functions. "The results identified one potential KS candidate gene (TSPAN11), seven candidate genes for the neurodevelopmental disorder (TM7SF3, STK38L, ARNTL2, ERGIC2, TMTC1, DENND5B, and ETFBKMT), and four candidate genes for KS with ID (INTS13, REP15, PPFIBP1, and FAR2)." (PMID 37034680, 2023). "As a result, we identified a dozen candidate genes: TSPAN11 as a potential KS candidate gene, TM7SF3, STK38L, ARNTL2, ERGIC2, TMTC1, DENND5B, and ETFBKMT as candidate genes for the neurodevelopmental disorder, and INTS13, REP15, PPFIBP1, and FAR2 as candidate genes for KS with ID." (PMID 37563198, 2023).
kidney disease (1 paper, 2020). "FAR2 is strongly associated with kidney disease and a strong expression was found in the IgAN group characterized by active renal lesions." (PMID 32938960, 2020).
FAR2 also shares sentences with these, for which no sentence is quoted: neurological disorder (2 papers); tumor (2); Atrophy (1); bipolar disorder (1); cataract (1); cicatricial alopecia (1); colon cancer (1); diffuse large B-cell lymphoma (1); Hypertension (1); IgA nephropathy (1); lung carcinoma (1); lupus nephritis (1); parasitic infection (1).